IL6 (interleukin 6)
Diseases named in the same sentence as IL6 in open-access papers (continued):
Sharing a sentence is not in itself a finding about the gene and the disease.
Alzheimer disease (continued). "IL-6-mediated inflammation is known to cause higher incidence of gliosis and dendritic damage in patients with neurological diseases such as Parkinson’s disease (PD) and Alzheimer’s disease (AD)." (PMID 41465427, 2025). "As IL‐6 has been linked with the pathophysiology of tauopathies such as Alzheimer's disease [S90], anti‐IL‐6 strategies may prove beneficial for PSP." (PMID 37574254, 2023). "It was reported that increased inflammatory response was implicated in neurodegenerative disorders, including Alzheimer’s disease, PD and amyotrophic lateral sclerosis, and a meta-analysis demonstrated that the expression of IL-1β, IL-6, and TGF-β were upregulated in PD." (PMID 34967706, 2022). "In addition to its neuroprotective role, IL-6 has been implicated in the pathogenesis of autoimmune and inflammatory diseases, including multiple sclerosis, and Parkinson’s and Alzheimer’s disease." (PMID 35056000, 2022). "Of note, observational and genetic evidence has supported an association of low CRP levels with increased risk of Alzheimer’s disease, and further work is required to delineate the dose–response relationship between IL-6 signaling mediated changes in CRP levels and potential adverse outcomes." (PMID 35948913, 2022). "SNPs in IL‐6 are implicated in Alzheimer's disease, sclerosis and myasthenia gravis." (PMID 34599867, 2021). "Blood levels of IL-6 are significantly elevated in individuals with Alzheimer's disease, and polymorphisms in the IL-6 gene that decrease plasma IL-6 levels may be associated with a lower risk of developing Alzheimer's disease." (PMID 33362607, 2020). "Single studies have reported that carriers of the A allele of the TNF-α 308 G/A gene were variably associated with increased risk of Alzheimer’s disease and that carriage the higher IL-6 producing allele of IL-6 (174 G/C) may confer increased risk." (PMID 29686666, 2018). "Considering each of these factors separately, this does not seem to match previous findings, as prior studies have shown positive associations between for instance Alzheimer’s disease and increased levels of several cytokines, and between aging and increased levels of IL-6 and TNF-α." (PMID 30261848, 2018). "Accordingly, Calogero Caruso (University of Palermo, Italy) reviewed the reports indicating an association between the risk of Alzheimer Disease (AD) and polymorphisms of genes encoding inflammatory mediators, such as IL-1β, IL-6, IL-10 and TNF-α, as well as the possible involvement of Zn." (PMID 17883856, 2007). "Furthermore, oxidative damage leads to an increase in IL-6 production, which has been shown to inhibit Foxp3 expression in Treg differentiation, suggesting that oxidative stress is the cause of a decrease of Treg levels in patients with Alzheimer’s disease." (PMID 40078868, 2025). "Elevated levels of IL-1β, IL-6, MCP-1, and TNF-α, alongside reduced IL-8 and IL-10 levels, suggest a robust inflammatory response associated with Alzheimer’s disease." (PMID 40711681, 2025). "AVE0991 treatment in the APP/PS1 double-transgenic mouse model of Alzheimer’s disease suppressed astrocyte-mediated inflammation by downregulating the expression profile of IL-1β, IL-6, and TNF-α in the brain cortex." (PMID 40565247, 2025). "For example, curcumin-loaded nanoparticles attenuated microglial activation, decreased levels of neurotoxic cytokines (TNF-α, IL-6), and improved cognitive performance in Alzheimer’s disease (AD) models." (PMID 40807355, 2025). "Cytokines such as TNF-α and IL-6 stimulate the expression of NFκB, leading to the production of Aβ in the brains of patients with Alzheimer’s disease." (PMID 40507988, 2025). "For example, in animal models of epilepsy, Alzheimer’s disease, and interleukin 6 overexpression, interneurons were specifically affected, while other types of neurons were not." (PMID 41008554, 2025).
Alzheimer disease (continued). "For instance, in mice, bacterial EVs can cross the BBB and activate inflammatory signaling pathways like TLR8 and NF-κB, or activate IL-6 and NF-κB in brain monocytes and microglia, contributing to neuroinflammatory diseases such as Alzheimer’s disease." (PMID 39000150, 2024). "Others have reported that AD-16 was able to reduce IL-1β expression induced by LPS in vivo, restore IL-4 and IL-6 levels in a mouse model of Alzheimer’s disease, and reduce IL-1β and TNF-α levels in the brain of ischemic mice." (PMID 39736920, 2024). "In Alzheimer’s disease (AD), characterized by amyloid beta (Aβ) plaque accumulation and tau pathology, IL-6 influences Aβ production and clearance." (PMID 39015561, 2024). "The role of IL-6 in episodic memory functioning has been demonstrated in studies on mice and patients with Alzheimer’s disease." (PMID 38840166, 2024). "Using an animal model for Alzheimer’s disease, it was also reported that AD-16 improved short-term and long-term memory, restored the IL-4 and IL-6 levels in the brain, and protected neurons." (PMID 39736920, 2024). "More recently, it was reported that treatment with Tan IIA reduced the expression of proinflammatory cytokines such as NF-κB, TNF-α, IL-6, and IL-1β in Alzheimer's disease model." (PMID 39687171, 2024). "IL6 is a well know biomarker in diseases of the central nervous system (CNS), such as Alzheimer’s Disease (AD), Parkinson’s Disease (PD) or Huntington’s disease (HD), due to its consistent upregulation whenever neuroinflammation is expected." (PMID 39055316, 2024). "The role of IL-6 in the pathogenesis of Alzheimer’s disease has been extensively studied and summarized in numerous meta-analyses." (PMID 39201378, 2024). "Another typical SASP factor, IL-6, is commonly upregulated in the aging brain and patients with Alzheimer’s disease, and its overexpression has been demonstrated to induce neurodegeneration in vitro." (PMID 37569663, 2023). "It was also reported that levels of peripheral cytokines, such as IL-1β, TNF-α, IL-6, and C reactive protein, were significantly higher in elderly with Alzheimer’s disease." (PMID 37623235, 2023). "Taken together, our data substantiate that the H3K18la/NFκB signaling axis regulates IL-6 and IL-8, which affect brain aging and Alzheimer's disease phenotype." (PMID 37697347, 2023). "Another cytokine that is important for the development of neuroinflammation in Alzheimer’s disease is IL-6." (PMID 37047492, 2023). "In cerebral hypoperfusion and Alzheimer's disease models, activated glia was shown to release proinflammatory factors such as IL-1β, IL-6, TNF-α, COX-2, and iNOS, promoting further neuronal degeneration in the hippocampus." (PMID 37064799, 2023). "Persistent low-grade inflammation in the brain has been reported to exacerbate neurodegenerative pathologies, including PD and Alzheimer diseases, with pro-inflammatory cytokines such as IL-1β and IL-6 considered key drivers." (PMID 38110963, 2023). "RAGE inhibition with azeliragon in patients with Alzheimer’s disease showed a prominent reduction in plasma levels of IL-6 as well as other cytokines." (PMID 36652782, 2023). "In view of evidence that cytokine (e.g., IL-6) levels appear to be inversely correlated with hippocampal volume, it has been hypothesized that IL-6 may potentiate memory impairment, playing a possible pathogenic role in Alzheimer’s disease (AD), vascular dementia, and age-related cognitive decline." (PMID 37046878, 2023). "IL-6 expression is involved in the synthesis of beta-amyloid precursor protein being altered in the brains of Alzheimer’s disease (AD) patients and it is also upregulated whenever neuroinflammation is expected, such as infection or injury." (PMID 37251808, 2023).
Alzheimer disease (continued). "IL-1 beta, IL-6, IL-10, and TNF-alpha single nucleotide polymorphisms in human influence the susceptibility to Alzheimer’s disease pathology." (PMID 35966781, 2022). "During the last decade, IL-6 has been identified as a biomarker for several neuroinflammatory diseases, including depression and Alzheimer’s disease." (PMID 36778590, 2022). "For example, p38 MAPK activation via multiple pathways is necessary for the productions of IL-1, IL-6, TNF-α, COX-2, and iNOS, implying that p38 MAPK activity is associated with the hallmark lesions of Alzheimer’s disease." (PMID 35214883, 2022). "IL-6 upregulates NMDA receptors, inducing neurotoxicity; this is one of the main mechanisms causing neurodegenerative disorders, including Alzheimer’s disease." (PMID 35736871, 2022). "IL-6 is secreted by macrophages in response to specific microbial molecules called pathogen-associated molecular pattern (PAMP), and increased expression of IL-6 is observed in neurodegenerative disorders such as PD and Alzheimer’s disease." (PMID 33652920, 2021). "In summary, the present study indicated for the first time that B. spectabilis flower decoction was able to reduce brain oxidative stress, IL-6, and the accumulation of amyloid Aβ in the AlCl3-induced model of Alzheimer’s disease in rats." (PMID 35096303, 2021). "Among 141 patients with Alzheimer’s disease (AD), a good correlation between plasma and CSF levels of IL-6 levels was reported (r = 0.76, p < .001)." (PMID 33931093, 2021). "Phosphorylated STAT3, TNFα, and IL-6 were also downregulated in the presence of anatabine in a transgenic mouse model of Alzheimer’s disease." (PMID 32855621, 2020). "For this view, IL6 is an important cytokine both in two closely related diseases Alzheimer’s disease and T2DM." (PMID 33150068, 2020). "Altered IL-6 expression is found in CSF and around amyloid plaques in the brain of Alzheimer's disease (AD) patients." (PMID 32508844, 2020). "Elevated levels of hippocampal IL-6 are thought to be related to neurodegeneration in the early stages of Alzheimer’s disease." (PMID 31730654, 2019). "On the contrary, several studies have reported that activation of MC4R obviously inhibited the overexpression of TNF-α, IL-6, and IL-1β in cerebral ischemia, Alzheimer’s disease, and subarachnoid hemorrhage." (PMID 29642894, 2018). "Numerous neurological disorders, such as multiple sclerosis and Parkinson’s and Alzheimer’s disease, are characterized by elevated levels of IL-6 in the CNS." (PMID 29921762, 2018). "A recent meta-analysis study reported significantly higher levels of the proinflammatory cytokines TNF-α, IL-6, IL-1β, IL-2, and IL-18 in peripheral blood samples of patients with Alzheimer's disease (AD) compared with a control group." (PMID 30510525, 2018). "The levels of pro-inflammatory cytokines, such as tumor necrosis factor-α (TNF-α), interleukin-6 (IL-6), are elevated in Alzheimer’s disease (AD) brains." (PMID 27287266, 2016). "In the central nervous system, IL-6 and IL-6R promote chronic inflammation and contribute to neurodegeneration and the development of Alzheimer's disease." (PMID 27119508, 2016). "Previous work by Luterman and colleagues showed a similar pattern in patients with late/terminal Alzheimer’s disease exhibiting greater amounts of IL-6 mRNA in entorhinal cortex and temporal gyrus compared to controls." (PMID 26376776, 2015). "An involvement of interleukin (IL)-6 has in particular been suggested as altered levels of IL-6 in cerebrospinal fluid (CSF) have been found in patients with Alzheimer’s disease (AD)." (PMID 26434635, 2015). "IL-6 has also been shown to be significantly elevated in cases of traumatic brain injury, Alzheimer’s disease and Huntington’s disease." (PMID 25815475, 2015). "The cytokine IL-6 has been shown to play a role in the immune response, inflammation and hematopoiesis, and in neuroimmunomodulation in Alzheimer’s disease." (PMID 24675728, 2014).
Alzheimer disease (continued). "The cytokine IL-6 is a biomarker of brain aging, and high levels of IL-6 are found in senescent cells and Alzheimer disease brains." (PMID 22384090, 2012). "Increases in IL-6, CCL2 and CXCL8 are associated with activation of perivascular macrophages and glia, and with the development of neurological diseases such as HAND, Alzheimer’s disease, Parkinsons’s or Huntington’s disease, and multiple sclerosis." (PMID 22901451, 2012). "Interleukin 6 (IL-6) has been related to beta-amyloid aggregation and the appearance of hyperphosphorylated tau in Alzheimer's disease (AD) brain." (PMID 22272811, 2012). "IL6 plasma and CSF levels have been reported to be increased in Alzheimer's disease and the secretion of IL6 from monocytes is increased." (PMID 22254144, 2011). "Pathological upregulation of astrocytic IL-6 expression is known to play a pivotal role in onset and progression of neurological diseases including Alzheimer's disease, multiple sclerosis, Parkinson's disease and traumatic brain injury." (PMID 21801384, 2011). "Elevated levels of IL-6 are typical for brains from animal models or humans suffering from multiple sclerosis, Alzheimer's disease, Parkinson's disease, lethal sepsis, meningitis and stroke." (PMID 21801384, 2011). "An inflammatory state has been documented in senile plaques and surrounding glia with an increased expression of the acute phase protein CRP as well as pro-inflammatory interleukins such as IL-6 and IL-1 in Alzheimer's disease (AD) patients and animal models." (PMID 20205886, 2010). "It is well known that IL-6 with other cytokines have been the subject of many studies of biomarkers for Alzheimer's disease." (PMID 18769539, 2008). "Similarly, individuals affected by Alzheimer’s disease exhibit hypomethylation of pro-inflammatory genes such as TNFα and Il6, potentially contributing to neuronal damage and chronic neuroinflammation." (PMID 40867210, 2025). "Moreover, thymol demonstrated dose-dependent anti-inflammatory effects in an Alzheimer’s disease model, significantly reducing serum and hippocampal levels of IL-1, IL-6, TNF-α, and COX-2, with optimal effects at 80 mg/kg." (PMID 40430456, 2025). "Another study in a mouse model showed that a decrease in IL-10 activates microglia cells, leading to an increase in IL-6 levels and inducing hyperphosphorylation of the tau protein on epitopes key to Alzheimer’s disease in response to acute systemic inflammation." (PMID 40507988, 2025). "Similarly, we found that Fli-1 in brain pericyte contributes to the inflammatory response in the brain in Alzheimer’s disease, where inhibition of Fli-1 reduced inflammatory mediators such as IL-6 in the hippocampus." (PMID 39862276, 2025). "To date, there are few clinical trials with highly variable results regarding the pro-cognitive effect of IL-6 modulators; most of these studies have been conducted in samples of patients with Alzheimer’s disease, making direct extrapolation to our population of interest difficult." (PMID 40650149, 2025). "For example, postmortem analyses have revealed increased levels of IL-1β and IL-6 in the hippocampi of aged humans, supporting the inflammatory hypothesis of early Alzheimer’s disease (AD) pathogenesis." (PMID 39301197, 2024). "Moreover, at early stages of HD, elevated IL6 levels are thought to have protective effects, similar to those in animal models of traumatic brain injury, Parkinson and Alzheimer diseases." (PMID 37992314, 2024). "Additionally, the systemic infusion of IL-6 NAb attenuates the increase in BBB permeability caused by ischemia, while high levels of IL-6 promote BBB disruption and decrease Pgp in Alzheimer’s disease." (PMID 39487455, 2024). "Inflammatory cytokines TNF-α and IL-6 secreted by microglial M1 macrophages and Angptl2 have been shown to induce neuroinflammation and participate in the progression of neurodegenerative diseases, such as Alzheimer’s disease." (PMID 38785563, 2024).
Alzheimer disease (continued). "In Alzheimer’s disease, neuroinflammation mediates the upregulation of the activated microglia (the pro-inflammatory M1 phenotype) with increased release of the pro-inflammatory factors, mainly interleukin-6 (IL-6)." (PMID 38236457, 2024). "Interestingly, in patients with Alzheimer’s disease, significantly decreased LPS-induced release of IL-6 and IL-1β in PBMC after six months of omega-3 supplementation (2.3 g/day) was reported." (PMID 36674453, 2023). "In this regard azeliragon was able to reduce IL-6 levels in patients with Alzheimer’s disease." (PMID 36652782, 2023). "Astrocytes have been shown to take on a senescence phenotype following treatment with amyloid-beta oligomers, and astrocytes expressing the senescent markers p16INK4a and IL-6 have been found in the frontal cortex of aged patients, Alzheimer’s disease patients, and around amyloid plaques." (PMID 37533101, 2023). "Furthermore, in the hippocampus, evodiamine significantly reduces neuroinflammation (TNF-α, IL-1β, and IL-6) and glial cell activation, rendering it a potential treatment for neurodegenerative diseases such as Alzheimer's disease." (PMID 37497547, 2023). "Recent findings also support the idea that target pro-inflammatory IL-6 signaling may be a strategy to alleviate memory impairment in patients with Alzheimer’s disease." (PMID 38093175, 2023). "Studies have shown that in the course of Alzheimer’s disease, cells that are sensitive to IL-6 shed from their surface the receptors that are responsible for binding this cytokine, leading to a decrease in its activity and abolition of its pro-inflammatory effect on neurons in AD patients." (PMID 37047492, 2023). "IL-6 is capable of exerting activities that are diametrically opposed to one another, such as promoting neuronal survival after injury or contributing to neuronal degeneration and cell death in conditions such as Alzheimer's disease." (PMID 36333451, 2022). "This correlation between the SNP of IL‐6 and the pathogenesis of glaucoma still remains unclear, although it was shown to be involved in the pathogenesis of Alzheimer's disease." (PMID 34599867, 2021). "Studies have shown that exercise-induced IL6 can attenuate memory impairment in models of Alzheimer’s disease, whereas in the hypothalamus, IL6 produced in response to exercise can reduce diet-induced inflammation and correct the abnormal regulation of food intake." (PMID 34465367, 2021). "In particular, Ag nanoparticle was confirmed to cause Aβ deposition in neuronal cells, and subsequently enhance the secretion of MCP-1 and IL-6 and induce neuronal cell apoptosis, and these biological alterations finally promoted the pathogenesis of Alzheimer’s disease." (PMID 33639958, 2021). "Indeed, our group is currently analyzing the role of IL-6 in a mouse model of Alzheimer’s disease and in a mouse model of progressive encephalopathy resembling Leigh syndrome using this novel strategy." (PMID 33059703, 2020). "Several studies on the brain reported that inhibition of IL-6 trans-signaling in microglia and neurons attenuated lipopolysaccharide (LPS)-induced sickness behavior in mice and also attenuation of IL-6 trans-signaling mediated neuroinflammation in Alzheimer’s disease models of mice." (PMID 32848763, 2020). "For instance, IL-6, an inflammatory cytokine, is known to mediate many undesired, detrimental effects that contribute to cardiovascular disease, bowel disease and Alzheimer disease." (PMID 30947706, 2019). "Several pro-inflammatory cytokines, including IL-1β, IL-6, IL-8 and TNF-α have been implicated in neuroinflammation in a variety of neurodegenerative diseases including Alzheimer’s disease, Parkinson’s disease (PD), multiple sclerosis and HIV-associated neurocognitive disorders (HAND)." (PMID 25539898, 2014).